UCHL1 (ubiquitin C-terminal hydrolase L1)
Diseases named in the same sentence as UCHL1 in open-access papers (continued):
Sharing a sentence is not in itself a finding about the gene and the disease.
tumor (continued). "Transfection with the UCHL1(C90S) mutant failed to rescue the tumor-promoting effect of NPC cell migration and invasion, which implied that the ligase activity of UCHL1 is indispensable for UCHL1 mediated-suppressive effects on NPC cell migration and invasion." (PMID 32120844, 2020). "Taken together, these results indicate that UCHL1 is downregulated in NPC and other tumor types." (PMID 32120844, 2020). "One hundred and fourteen matched human NSCLC tumor/normal pairs were examined by real-time q-PCR analysis for expression of PARK1/4 (SCNA), PARK2 (Parkin), PARK5 (UCHL1), PARK6 (PINK1), PARK7 (DJ-1), PARK8 (LRRK2), PARK9 (ATP13A2), PARK15 (FBXO7), and GBA mRNA." (PMID 26245297, 2015). "In the present experiments, UCHL1 expression was absent/weak in normal cells, but highly expressed in tumor cells." (PMID 25971332, 2015). "UCHL1, also called protein gene product 9.5 (PGP9.5), is a member of the ubiquitin carboxyl-terminal hydrolase family and plays a role in the development of many tumor types via aberrant promoter methylation." (PMID 26550574, 2015). "The in vivo murine model of pulmonary metastasis also demonstrated that LDN57444 did not inhibit metastatic tumour formation when the endogenous expression of UCHL1 was low (EV), but did when UCHL1 was reconstituted (UCHL1)." (PMID 25615526, 2015). "We used the small-molecule UCHL1 inhibitor, LDN57444, to establish whether UCHL1 could be exploited as a therapeutic target to reduce the incidence of distant tumour metastases." (PMID 25615526, 2015). "Survival analysis revealed that SNAT1 is an important predictor for tumor recurrence and prognostic factor for HC patients, while UCHL1 and EGR1 was not a significant indicator of prognosis." (PMID 25971332, 2015). "Although the overexpression of UCHL1 did not promote the growth of primary tumour xenografts in the mammary fat pad, the number of metastatic colonies was markedly increased by the forced expression of UCHL1." (PMID 25615526, 2015). "UCHL1 expression showed a positive correlation with normal brain tissue and low-grade tumor, and a negative correlation with high-grade tumors." (PMID 25050814, 2014). "Methylation specific PCR analysis results showed a highly methylated promoter region for UCHL1 in 90% (18/20) of tumor tissue compared to 15% (3/20) of normal tissues from PCa patients." (PMID 21999842, 2011). "Finally, while 15 DUBs were found to be significantly dysregulated in only one type of cancer, 7 (UCHL1, USP9X, USP11, USP10, USP22, COPS5 and COPS6) displayed multiple alterations in two or more tumor types." (PMID 21283576, 2011). "The reexpression of UCHL1 in metastatic RCC indicated a tumor stage-specific UCHL1 hypomethylation suggesting that UCHL1 acts as an oncogene rather than as a tumor suppressor gene." (PMID 19857250, 2009). "Significantly elevated levels of UCHL1 were observed in the blood serum and exosomes of TNBC patients, suggesting that UCHL1‐containing exosomes could potentially serve as a biomarker for early detection of metastasis in tumours." (PMID 40032646, 2025). "In addition, UCHL1‐specific inhibitor, LDN‐57444, significantly reduced NE markers expression, as well as delayed tumor growth of multiple NE carcinoma xenografts, including NEPC (NCI‐H660), SCLC (NCI‐H82), and neuroblastoma (IMR‐32) cell line, and NEPC and SCLC PDX models in vivo." (PMID 39372390, 2024). "However, the correlation between UCHL1 expression and clinicopathologic features in NB and the effect of UCHL1 on biological behaviors of NB tumor cells are not well understood." (PMID 30359286, 2018). "Overall, the COBRA analyses revealed that 12/32 primary RCC lesions could be classified as partially methylated in regard to their UCHL1 promoter, whereas no methylation was found in the tumor adjacent kidney epithelium." (PMID 19857250, 2009).
tumor (continued). "In addition, the reductions in CD133‐positive tumour cells and Notch1 protein in UCHL1‐knockdown PDOs could not be restored by DETA NONOate treatment, confirming the Notch1 deubiquitylation and CSC maintenance as downstream consequences of NO metabolism." (PMID 39523215, 2024). "However, any relationship to simple mRNA expression should be treated with caution, since UCHL1 transcript level may not correlate with UCHL1 protein expression, which in turn may not correlate with UCHL1 enzyme activity in the tumour." (PMID 34497382, 2022). "In multivariable analysis, increment in every unit of UCHL1 mRNA correlated with a decrease in HR for OS (HR: 0.338, 95% CI: 0.116–0.980, P = 0.046) and EFS (HR: 0.476, 95% CI: 0.228–0.994, P = 0.048) independent of established risk markers (MYCN status, tumor stage and patient age at diagnosis)." (PMID 30359286, 2018). "This analysis revealed a noteworthy upregulation in the expression levels of SNRNP200 and downregulation of UCHL1 and PAK4 proteins in the CPTAC tumor samples compared to normal samples." (PMID 39199615, 2024). "The BPDCN microenvironment resulted negative for neural markers but, surprisingly, the tumor cells themselves were positive for the 2 progenitor neural markers: DCX and UCHL-1, in 11/15 (73.3%) and 15/15 (100%) cases, respectively." (PMID 34572907, 2021). "Through a literature survey, we identified that GPX3, LDOC1, LXN, and UCHL1, but not LIPG, have been reported as tumor suppressor genes, and that their expression was mediated by promoter DNA methylation." (PMID 26317789, 2015). "The established cell lines, with the expression of porcine SSC and germ cell markers UCHL1, PLZF, THY1, VASA and DAZL, could respond to retinoic acid (RA), and could colonize the recipient mouse testis without tumor formation after transplantation." (PMID 32308978, 2020). "We here extended these data and determined whether the promoter DNA methylation also contributes to the lack of UCHL1 expression in 32 pairs of primary RCC lesions and corresponding tumor adjacent kidney epithelium as well as 17 RCC cell lines." (PMID 19857250, 2009).
cancer (141 papers, 2009 to 2026). A tumor composed of atypical neoplastic, often pleomorphic cells that invade other tissues. "UCHL1 knockdown using siRNA significantly suppressed cancer-associated phenotypes, including cell proliferation, migration, and invasion." (PMID 41155583, 2025). "The abnormal expression of UCHL1 is implicated in the pathogenesis of multiple diseases, such as nervous system diseases, cancer, and lung diseases." (PMID 38727276, 2024). "Cancer usually accompanies the development of inflammation, and studies have shown that UCHL1 is associated with ovarian cancer." (PMID 36218038, 2023). "Loss of the DUB UCHL1 leads to neurodegeneration, and its dysregulation promotes cancer metastasis and invasiveness." (PMID 36216817, 2022). "The deubiquitinase UCHL1 has been linked to cancer invasiveness and neurodegeneration yet its molecular roles have remained poorly defined." (PMID 36216817, 2022). "This suggests that pharmacological inhibition of UCHL1 is a potential therapeutic avenue for treatment of UCHL1-implicated cancers." (PMID 33668938, 2021). "Ubiquitin C-terminal Hydrolase L1 (UCHL1) is a 25 kDa DUB whose ectopic expression is linked to a number of cancers." (PMID 33668938, 2021). "The deubiquitinating enzyme (DUB) UCHL1 is implicated in various disease states including neurodegenerative disease and cancer." (PMID 33668938, 2021). "The contrary roles of UCHL1 have been reported in different types of cancers, associated with poor or better survival." (PMID 30359286, 2018). "Despite the fact that UCHL1 has been linked with neurodegenerative diseases and a wide range of cancers, its physiological role remains elusive." (PMID 29126443, 2017). "Ubiquitin C-terminal hydrolase isozyme L1 (UCHL1) is primarily expressed in neuronal cells and neuroendocrine cells and has been associated with various diseases, including many cancers." (PMID 29126443, 2017). "Loss-of-function studies and an inhibitor for UCHL1 confirmed the importance of UCHL1 for cancer therapy." (PMID 25615526, 2015). "Ubiquitin C-terminal Hydrolase L1 (UCH L1) has been linked to several neurological diseases as well as human cancer, but the physiological targets and the regulation of UCH L1 expression in vivo have been largely unexplored." (PMID 19536331, 2009). "UCHL1, which is a member of DUBs, is associated with chemoresistance in many cancers." (PMID 33718207, 2021). "UCHL1 loss and overexpression has been reported in numerous cancer types." (PMID 31906456, 2020). "In addition, the pro-activation effect of UCHL1 is observed in other types of fibroblasts, such as cancer-associated fibroblasts and hepatic stellate cells." (PMID 32606430, 2020). "Increasing data has indicated that UCHL1 plays an important role in proliferation, neoplasm metastasis, oxidative stress and immune responses, and it has been implicated in the development of neurodegenerative diseases and cancer." (PMID 31700166, 2020). "We then performed conventional in vitro clonogenic cell survival assays to investigate whether UCHL1 causes the radioresistance of cancer cells in a HIF-1-dependent manner." (PMID 28761052, 2017). "Finally, within the list of upregulated genes in the UCHL1 KD we also found several cancer-associated genes such as SERPINB4, FGF21, NUPR1, SBSN, GDF1, HMOX1, or SOCS2, which suggested the activation of potential compensatory mechanisms in these KDs cells." (PMID 28472177, 2017). "Except for CNS, UCHL1 is also expressed in the testis and ovaries, and its increased expression was reported in different types of cancer (e.g., brain, lung, breast, kidney, colon, prostate, pancreas)." (PMID 40141757, 2025).
cancer (continued). "Conversely, other researchers have characterized UCHL1 as an oncogene in cancers such as non-small-cell lung cancer, lymphoma, prostate cancer, colorectal cancer, melanoma, and osteosarcoma." (PMID 40141757, 2025). "Subsequently, we analyzed the correlation between UCHL1 expression in each subtype of TCGA-BRAC cancer tissue and the corresponding UCHL1 DNA methylation level in the tissue." (PMID 38468288, 2024). "To explore the mechanisms of UCHL1 dysregulation, we merged and compared the expression data of UCHL1 from the GTEx (normal tissue sequencing data) and TCGA databases (cancer and adjacent tissue)." (PMID 38468288, 2024). "UCHL1 is a deubiquitinating enzyme (DUB) known to be highly expressed in neurons and previously implicated in neurodegeneration and several forms of cancer, but poorly characterized in bone biology." (PMID 38538704, 2024). "It would therefore be of great value to investigate the efficacy of UCHL1 inhibitors in treating cancer cell types with elevated UCHL1 and HIF activity." (PMID 38808772, 2024). "As UCHL1 can deubiquitinate and stabilise HIF1α in cancer cell lines, we sought to determine if there are changes in HIF1α levels during HSC transdifferentiation." (PMID 38808772, 2024). "According to previous reports, UCHL1 is frequently overexpressed in neurons and highly expressed in certain cancer cells." (PMID 36830563, 2023). "Knockdown of CHGA and UCHL1 significantly regulate cancer behaviours of HCT‐116, including inhibition of cell migration, invasiveness, cell cycle G1/S arrest and reactive oxygen species (ROS) generation." (PMID 37246623, 2023). "In this context, the in-silico drug screening approach revealed several drugs with a higher efficacy for UCHL1-related cancer cells from CCLE." (PMID 36980544, 2023). "With the identification of UCHL1-related tumors, we established a novel cancer subgroup with distinct molecular traits and favorable prognosis after radiotherapy." (PMID 36980544, 2023). "In this study, a new subgroup of UCHL1-related cancers was identified across multiple solid tumor entities and was characterized by comprehensive multi-omics analysis." (PMID 36980544, 2023). "An extreme gradient boosting model was trained on TCGA-HNSC based on GSVA scores for gene sets of the MSigDB to robustly predict UCHL1-related cancers in other solid tumors and cancer cell lines derived thereof." (PMID 36980544, 2023). "PRISM confirmed a significant difference (p < 0.01) in response for 19 compounds, of which the majority (n = 14) were more effective in UCHL1-related as compared to other cancer cell lines." (PMID 36980544, 2023). "To validate these findings, we analyzed the viability data from the independent PRISM drug screen for UCHL1-related and other cancer cells." (PMID 36980544, 2023). "UCHL1-related HNSC were characterized by higher frequencies of genomic alterations, which was also evident for UCHL1-related cancers of other solid tumors predicted by the classification model." (PMID 36980544, 2023). "First, effective compounds with a significant difference in z-scores between UCHL1-related and other cancer cells were identified from GDSC." (PMID 36980544, 2023). "Potential vulnerabilities of UCHL1-related cancer cells were elucidated by an in-silico drug screening approach." (PMID 36980544, 2023). "Cancer cells resembling a UCHL1-related phenotype had a significantly lower integral survival after irradiation, confirming an intrinsically higher RT sensitivity." (PMID 36980544, 2023). "The deubiquitinase UCHL1 is an oncoprotein that promotes the growth and progression of cancer cells." (PMID 36968845, 2023). "In this study, we demonstrated a prominent UCHL1 expression in cancer cells for a substantial amount of primary HNSC at transcript and protein levels." (PMID 36980544, 2023). "UCHL1 is a de-ubiquitinating enzyme that has been found to be over-expressed in some cancers and is considered a cancer promoter." (PMID 37575253, 2023).
cancer (continued). "Common features of UCHL1-related cancers are an increased genomic instability and a vulnerability to DNA-damaging treatment, which is accompanied by a favorable prognosis after radiotherapy." (PMID 36980544, 2023). "In line with this assumption, UCHL1-related cancer cell lines had a significantly higher expression of a gene set related to DNA repair pathways." (PMID 36980544, 2023). "Altered UCHL1 expression and function has been reported across several human cancers, suggesting the presence of UCHL1-related tumors with similar mutational and molecular landscapes beyond HNSC." (PMID 36980544, 2023). "UCHL1 is a well-known deubiquitinase with essential roles in regulating neurodegenerative diseases, cancer, and even cardiac function by abrogating the ubiquitination of many target proteins." (PMID 37797697, 2023). "A highlight of our study is the differences in the survival of cancer patients stratified by the classification model specifically after radiotherapy, indicating an increased radiosensitivity for UCHL1-related tumors." (PMID 36980544, 2023). "A novel classification model has been established for accurate identification of UCHL1-related cancers, leveraging further basic and translational research on this novel cancer subgroup." (PMID 36980544, 2023). "This BODIPY-labeled probe can selectively target UCHL1 and emit fluorescence in zebrafish embryos and cancer cells." (PMID 35682614, 2022). "Lastly, the pro-cancer effect of UCHL1 is mechanistically correlated with activated Akt and ERK1/2 pathways." (PMID 36497313, 2022). "UCHL1 has been considered a cancer promoter due to its overexpression in certain type of cancers; however, its role in cancer initiation, progression and invasion are still a matter of debate." (PMID 34497382, 2022). "Although UCHL1 is expressed in normal tissues such as neurons, more and more evidence suggests that UCHL1 is upregulated in some human cancers and plays a critical role in cell proliferation, migration, invasion, and anti-apoptosis." (PMID 35546675, 2022). "Ubiquitin carboxy-terminal hydrolase L1 (UCHL1) is one of the key elements that promotes cancer progression as well as neurodegenerative diseases." (PMID 35682614, 2022). "We aimed to distinguish the differential compartmentalization of UCHL1 expression in tumors with respect to the frequency of UCHL1 expression in cancer cells." (PMID 35546675, 2022). "Both genetic depletion of UCHL1 as well as transfection to introduce a catalytically inactive UCHL1 mutant reduced the ability of various cancer cell lines to metastasize." (PMID 33668938, 2021). "The role of UCHL1 in cancer is complicated by the fact that it can act as an oncogene via many molecular mechanisms depending on the cancer type." (PMID 34257568, 2021). "To assess the specificity and universality of UCHL1, we analyzed transcript level of UCHL1 in 24 cancers and corresponding normal tissues." (PMID 34016791, 2021). "Previous studies have shown that UCHL1 is expressed at lower levels in healthy tissues, but it is highly induced in several forms of cancer and lung tumor cell lines." (PMID 31700166, 2020). "UCHL1 has also been reported to act as either an oncogene or tumor suppressor gene in different types of cancer." (PMID 32120844, 2020). "Normally ubiquitin C-terminal hydrolase L1 (UCH-L1) is expressed in the central nervous and reproductive systems of adults, but its de novo expression has been detected in many human cancers." (PMID 31370144, 2019). "Most of the cancer studies on UCHL1 have revealed that overexpression and promoter methylation of UCHL1 are key reasons for UCHL1-mediated metastasis." (PMID 29306329, 2018). "Due to the adverse effect of overexpression of UCHL1, it is considered to be a biomarker and a therapeutic target in many cancers." (PMID 29306329, 2018). "UCHL1 is a deubiquitinase highly expressed in the nervous system and its role in different types of cancer is starting to be elucidated." (PMID 28472177, 2017).